EGFR (epidermal growth factor receptor)
Diseases named in the same sentence as EGFR in open-access papers (continued):
Sharing a sentence is not in itself a finding about the gene and the disease.
colorectal cancer (continued). "In modern colorectal cancer treatment, chemotherapy is often combined with anti-EGFR antibodies to improve response rate." (PMID 32290033, 2020). "It has been proposed that c-Src kinase mediates the nuclear translocation of EGFR, an event that contributes to the acquired resistance to the anti-EGFR antibody cetuximab in colorectal cancer and head and neck squamous cell carcinoma (HNSCC)." (PMID 32517369, 2020). "We investigated a total of 25 colorectal cancer patient-derived TIC spheroid lines for sensitivity to pan-FGFR inhibitor erdafitinib as well as EGFR inhibitor, erlotinib." (PMID 32708005, 2020). "The longer half-life and higher affinity of panitumumab for EGFR, as well as the overexpression of EGFR, are responsible for a high incidence of grade 3/4 hypomagnesemia and hypokalemia in colorectal cancer patients." (PMID 32509580, 2020). "Here, we analyze how a common oncogenic KRAS mutation (KRASG13D) affects PPIN structure and function of the Epidermal Growth Factor Receptor (EGFR) network in colorectal cancer (CRC) cells." (PMID 31980649, 2020). "In a previous study, we have observed that RAS wild-type left-sided colorectal cancers are characterized by a lower EGFR protein expression as compared to those right-sided but respond significantly better to various anti-EGFR therapies." (PMID 32155907, 2020). "In our study, biomarker results such as EGFR were mostly found in the results of the immunohistochemical study report of colorectal cancer." (PMID 33295294, 2020). "Colorectal cancers are resistant to treatment with anti-EGFR monoclonal antibodies such as cetuximab or panitumumab." (PMID 31896739, 2020). "It was initially reported that EREG expression and the efficacy of the EGFR inhibitors are closely correlated in colorectal cancer." (PMID 32929368, 2020). "Analysis of large clinical trials indicated that the efficacy of anti-EGFR antibody therapies of advanced colorectal cancer patients is independent from EGFR expression levels." (PMID 32155907, 2020). "The phosphorylation level of IRE1α and the spliced XBP1s were aberrantly elevated in colorectal cancer, and IRE1α-XBP1s signaling activation was correlated with high EGFR expression." (PMID 32489465, 2020). "In this study, ~8% of patients harbored an EGFR amplification in their ctDNA, with EGFR amplifications being most common in colorectal cancer (16% of patients), NSCLC (9%), genitourinary cancers (8%), cutaneous tumors (7%), and breast malignancies (7%)." (PMID 32850413, 2020). "Targeting EGFR combined with chemotherapy is one of the most valuable therapeutic strategies in colorectal cancer." (PMID 32489465, 2020). "For example, Cet (anti-EGFR mAb) is used for the treatment of colorectal cancer and head and neck cancer, panitumumab (anti-EGFR mAb) has been approved for colorectal cancer, and necitumumab (anti-EGFR mAb) is used to treat squamous cell carcinoma of the lung." (PMID 32726945, 2020). "AXL dimerizes with epidermal growth factor receptor (EGFR), which has been shown to regulate FOXM1 expression via an EGFR/RAS/FOXM1/β-catenin axis in colorectal cancer." (PMID 32976773, 2020). "For colon cancer, cetuximab was first approved in Switzerland, USA, and EU from 2003 to 2004 as a second-line treatment for EGFR-positive unresectable advanced or recurrent colorectal cancer." (PMID 33383632, 2020). "EGFR activates the downstream kinase cascade and promotes colorectal cancer progression through the increased cell proliferation, prolonged survival, angiogenesis, anti-apoptosis, invasion, and metastasis." (PMID 32489465, 2020). "T-EVs generated by human lung or colorectal cancer cells transmit oncogenic EGFR to cultured ECs, through which they trigger EGFR-dependent reactions." (PMID 33081785, 2020).
colorectal cancer (continued). "Combination treatment with anti-EGFR monoclonal antibodies and chemotherapy is a common strategy for the treatment of patients with colorectal cancer; however, the efficacy of this treatment is limited 10–20% of such patients." (PMID 31896739, 2020). "In contrast, it has been reported that EGFR inhibitor gefitinib activated calcium release from the endoplasmic reticulum to suppress the growth of colorectal cancer cells." (PMID 33042262, 2020). "Taken together, chemotherapy in combination with BEV or anti-EGFR antibody drugs is recommended as first-line therapy for unresectable colorectal cancer, unless contraindicated." (PMID 31203527, 2020). "In the current treatment of colorectal cancer, the evaluation of EGFR and RAS expression from colorectal cancer resected specimens and biopsy specimens selects anticancer drugs and molecular targeted drugs that can be expected to have therapeutic effects." (PMID 32365822, 2020). "For example, therapeutic monoclonal antibodies against EGFR, such as Cetuximab and Panitumumab, are poorly effective in KRAS/NRAS-mutated colorectal cancers, that is, for ~40% of the patients." (PMID 32111026, 2020). "K57N is known to constitutively activate MEK1 in colorectal cancer cell lines, and we and others previously showed a role in EGFR-Ab resistance." (PMID 33322618, 2020). "In this study, we investigate the activation of IRE1α-XBP1s signaling in colorectal cancer, and demonstrate that EGFR signaling activates IRE1α through EGFR-MEK-ERK pathway." (PMID 32489465, 2020). "Among them, EGFR overexpression is an important mechanism of resistance to BRAF inhibitors in colorectal cancer patients." (PMID 32476297, 2020). "One of the targeted therapies for colorectal cancer is cetuximab which works by inhibiting the growth of cancer cells by targeting EGFR, so that there is inhibition in the MAPK pathway and decreased K-Ras expression." (PMID 32765634, 2020). "Some new drugs have recently been approved for the treatment of colorectal cancer and include epidermal growth factor receptor (EGFR) inhibitors." (PMID 32380712, 2020). "Our findings indicate IRE1α-XBP1s signaling is a potential therapeutic target and provides strong evidence to support the use of EGFR targeting in combination with chemotherapeutics for the treatment of colorectal cancer." (PMID 32489465, 2020). "We have previously developed an EGFR-targeted 4-1BB-agonistic trimerbody (1D8N/CEGa1) that induces potent anti-tumor immunity without systemic toxicity, in immunocompetent mice bearing murine colorectal carcinoma cells expressing human EGFR." (PMID 33488625, 2020). "PGE2 induces increased proliferation, migration, and invasiveness of colorectal carcinoma cells by phosphorylation of epidermal growth factor receptor EGFR and activation of the PI3K/AKT/mTOR signaling pathway." (PMID 32422889, 2020). "Panitumumab and cetuximab are two of the most commonly used mAbs in colorectal cancer and they target EGFR." (PMID 31169290, 2019). "PI3K activation plays a central role in the acquired resistance to the combination of anti-EGFR and MEK-inhibitor in KRAS mutated colorectal cancer cell lines." (PMID 30691487, 2019). "In colorectal cancers, tumour‐specific gene alterations of EGFR, BRAF, ALK, KIT, PDGFR, HER2 and KRAS75, 76, 77 were detected via ctDNA‐based assays." (PMID 30873683, 2019). "For instance, hyperactivation of STAT3 caused by EGFR inhibitors (STAT3 feedback activation) was shown to mediate resistance in lung cancer, colorectal cancer and glioma." (PMID 31422383, 2019). "Nimotuzumab-PEG6-DM1-Low and nimotuzumab-PEG6-DM1-High were used to treat EGFR positive KRAS mutant DLD-1 colorectal cancer xenograft." (PMID 30800216, 2019). "Only a small fraction of EGFR positive cancers represented by advanced colorectal cancers expressing wild type KRAS respond to anti-EGFR mAbs although acquired resistance also commonly occurs." (PMID 31508364, 2019).
colorectal cancer (continued). "KRAS mutations have been reported as a reliable biomarker for epidermal growth factor receptor (EGFR) targeted therapy and are also associated with poor prognosis in colorectal cancer (CRC) patients." (PMID 30791218, 2019). "Epidermal growth factor receptor (EGFR) supports colorectal cancer progression via oncogenic signaling." (PMID 30478887, 2019). "The multi-targeted TKI ponatinib was shown to inhibit STAT3 phosphorylation driven by EGFR and interleukin 6, leading to suppression of colorectal cancer cell growth and migration." (PMID 31422383, 2019). "Expression of the epidermal growth factor ligands amphiregulin (AREG) and epiregulin (EREG) is positively correlated with a response to EGFR-targeted therapies in colorectal cancer." (PMID 31370270, 2019). "EGFR proved to be central to colorectal cancer (CRC) patients, who often present addiction to this pathway." (PMID 31052457, 2019). "For example, resistance to anti-EGFR monoclonal antibodies in colorectal cancer and to EGFR TKIs in EGFR-mutant non-small cell lung cancer (NSCLC) can be mediated by activation of alternate RTK pathways including MET and HER2." (PMID 30759745, 2019). "For EGFR imaging, fluorescent monoclonal antibodies have been used in colorectal cancer to assess EGFR expression." (PMID 30612556, 2019). "In colorectal cancer, routine testing for KRASmut is now implemented as a predictor of response to anti-epidermal growth factor receptor (EGFR) therapy." (PMID 31111275, 2019). "TKIs are approved for NSCLC especially for cancers expressing mutated EGFR, whereas anti-EGFR mAbs are approved for KRAS wild-type colorectal cancer and local regional head and neck cancers." (PMID 31508364, 2019). "The epidermal growth factor receptor (EGFR) is an important therapeutic target in colorectal cancer (CRC)." (PMID 30650638, 2019). "Anti‐EGFR therapy is being investigated as a clinical option for colorectal cancer, and an observed interaction between EGFR and Prion protein has been detected in neuronal cells." (PMID 30478887, 2019). "Anti-EGFR antibodies are effective in therapies for late-stage colorectal cancer (CRC); however, many tumours are unresponsive or develop resistance." (PMID 31653970, 2019). "Overall, we have initially proved that lncRNA SLCO4A1-AS1 acts as an oncogene and promotes the development of colorectal cancer through the EGFR/MAPK pathway." (PMID 31853225, 2019). "Regarding colorectal cancer, the anti-EGFR antibodies cetuximab and panitumumab are used to treat RAS wild-type colorectal cancer, but their efficacy is limited due to the emergence of acquired drug resistance." (PMID 31169290, 2019). "Anti-epidermal growth factor receptor (EGFR) monoclonal antibodies such as panitumumab and cetuximab as single agents showed an activity in Kras wild-type colorectal cancer but presented limited benefits (1–2 months)." (PMID 32039017, 2019). "Since the early 1980s, aberrant expression of the epidermal growth factor receptor (EGFR) has been widely reported in a range of epithelial malignancies including colorectal cancer." (PMID 30899442, 2019). "Cetuximab is a monoclonal antibody employed in colorectal cancer (CRC) that binds to EGFR (epidermal growth factor receptor) inducing its degradation." (PMID 31867576, 2019). "This study investigated the co-expression and prognostic significance of the CSCs biomarkers CD44 and CD133 with wild-type EGFR (wtEGFR) and EGFRvIII in colorectal cancer (CRC)." (PMID 30899442, 2019). "Despite biomarker stratification, the anti-EGFR antibody cetuximab is only effective against a subgroup of colorectal cancers (CRCs)." (PMID 31287991, 2019). "Only three biomarker-drug-tumour combinations had both types of responses: the triplets ‘BRAF V600E-panitumumab, trametinib-colorectal cancer’, ‘EGFR R451C-cetuximab-colorectal cancer’ and ‘KRAS G13D-cetuximab-colorectal cancer’." (PMID 31169290, 2019).
colorectal cancer (continued). "Regarding molecular therapy for colorectal cancer, cetuximab has become widely used as a competitive inhibitor of epidermal growth factor receptor (EGFR)." (PMID 30805037, 2019). "The efficacy of monoclonal antibodies targeting the epidermal growth factor receptor (EGFR) pathway for treatment of colorectal cancer (CRC) depends on predictive biomarkers that can identify likely responders or non-responders to therapy." (PMID 31816869, 2019). "Colorectal cancer presents epidermal growth factor receptor (EGFR) overexpression and the use of aspirin can downregulate EGFR." (PMID 31311204, 2019). "The exceptions were the two epidermal growth factor receptor (EGFR) inhibitors for colorectal cancer, where panitumumab was priced over 160% higher than cetuximab, the first-of-kind." (PMID 31061053, 2019). "Of note, EGFR downregulation, because of the internalization and subsequent degradation of EGFR in lysosomes, has recently been reported to be an important determinant of the efficacy of cetuximab treatment for colorectal cancer." (PMID 30213849, 2019). "In vitro, the other experiments also indicated that taurine-conjugated bile acids activate Src, EGFR, and ERK, thereby causing colorectal cancer cells to proliferate." (PMID 30790117, 2019). "Retrospective comparison of colorectal cancer patients treated with anti-EGFR revealed that AREG expression is better than AREG gene methylation to predict clinical follow-up." (PMID 31370270, 2019). "EGFR-activation-mediated BRAF inhibitor resistance was described first in V600E BRAF-mutant colorectal cancer." (PMID 31514305, 2019). "An example of this comes from the analysis of circulating tumor DNA in the blood of colorectal cancer (CRC) patients with primary or acquired resistance to epidermal growth factor receptor (EGFR) blockade." (PMID 31247937, 2019). "Activating mutations in KRAS frequently occur in colorectal cancer (CRC) patients, leading to resistance to EGFR-targeted therapies." (PMID 31133691, 2019). "Understanding the mechanisms underlying these clinical observations is necessary to develop alternative strategies to overcome acquired resistance to EGFR targeting in colorectal cancer." (PMID 32039027, 2019). "This corresponds to other data showing that lung and colorectal cancer cells with resistance to EGFR-related TKIs displayed a rebound effect in cell proliferation after the treatment with anti-MET TKIs was interrupted." (PMID 31546690, 2019). "Basically, these results are in line with diagnostic and clinical experience regarding the administration of therapeutic antibodies targeting EGFR and a recent report on colorectal cancer organoids." (PMID 30925167, 2019). "In colorectal cancer (CRC), the RTK EGFR is overexpressed in more than 50% of cases and is linked to poor prognosis and metastasis." (PMID 30863492, 2019). "Finally, the clinical significance of RNAMethyPro was further exemplified in colorectal cancer, where high-risk patients demonstrated strong associations with a mesenchymal subtype, activated stromal infiltration, and poor therapeutic response to targeted anti-EGFR therapy." (PMID 31069256, 2019). "According to statistical analysis of the COSMIC database, colorectal carcinoma cells contain high rates of the gene mutation of KRAS (34%), PIK3CA (14%) and BRAF (10%), the major downstream signaling molecules of EGFR." (PMID 31367332, 2019). "Overexpression of EGFR is involved in the development of several types of cancers including colorectal cancer." (PMID 30187356, 2018).
colorectal cancer (continued). "Cetuximab is a monoclonal antibody approved for treatment of colorectal cancer which selectively binds EGFR to prevent the binding of natural EGFR-ligands and promote antibody-receptor complex internalisation." (PMID 29777377, 2018). "A greater understanding of colorectal cancer biology followed by use of EGFR-targeted treatments has led to discovery of the importance of BRAF, PIK3CA, KRAS, and NRAS mutations in predicting a lack of response to EGFR-targeted therapy." (PMID 29254887, 2018). "Three proteins that are over-expressed in colorectal cancer are epidermal growth factor receptor (EGFR), RAS and β-catenin." (PMID 30459318, 2018). "For example, colorectal cancer harboring KRAS mutation shows the resistance to cetuximab, an EGFR monoclonal antibody." (PMID 30497501, 2018). "Recently, in colorectal cancer (CRC) Cortactin overexpression inhibited the ubiquitin-mediated degradation of EFGR by suppressing the coupling of c-Cbl with EGFR." (PMID 30181811, 2018). "Overall, our results show that colorectal cancers are highly heterogeneous tumors at the intratumoral and intertumoral genetic levels, which probably affects the response to targeted anti-EGFR agents." (PMID 30344942, 2018). "Therapeutic protocols including EGFR antibodies in the context of oxaliplatin-based regimens have variable clinical effect in colorectal cancer." (PMID 30410004, 2018). "Salinomycin combined with orally active epidermal growth factor receptor inhibitor gefitinib synergized to induce apoptosis via mitochondrial-lysosomal cross-talk in colorectal cancer cells." (PMID 30531808, 2018). "OGN plays a restrictive role in colorectal cancer progression by reduced activation of EGFR/AKT/Zeb-1." (PMID 29499765, 2018). "Using an evolution-guided pY291-Fas proxy, RNA interference, and site-specific phospho-protein detection, we show that pY291-Fas significantly intensifies EGFR signaling in anti-EGFR-resistant colorectal cancer cells via the Yes-1/STAT3-mediated pathway." (PMID 30127519, 2018). "In colorectal cancer (CRC), mutations of EGFR downstream targets occur especially in the GTPase KRAS in up to 45% and in the phosphatidylinositol-4,5-bisphosphate 3-kinase, catalytic subunit alpha (PIK3CA) in up to 30% of patients." (PMID 30001368, 2018). "Here we report that the pro-survival form of Fas not only crosstalks with the EGFR but also significantly intensifies EGFR signaling in anti-EGFR-resistant colorectal cancer cells via the Yes-1/STAT3-mediated pathway." (PMID 30127519, 2018). "This important observation prompted us to investigate the connection between this pro-survival Fas in EGF-dependent EGFR signaling in colorectal cancer cells, which represents the type of cancer to which anti-EGFR therapy is widely applied." (PMID 30127519, 2018). "Since deregulation of epidermal growth factor receptor (EGFR) signaling commonly occurs in colorectal cancer and contributes to its progression, we decided to study how two selected miRNAs, namely miR-17 and miR-145, would affect EGFR endocytosis." (PMID 29459716, 2018). "There are two main complementary findings highlighted in this study: 1) a positive association between OGN and improved survival in primary CRC tumors; and 2) reduced activation of EGFR/AKT/Zeb-1 in colorectal cancer cells when OGN over-expressed." (PMID 29499765, 2018). "In conclusion, using an innovative and highly efficient screening approach we quickly identified two natural products (A and B) as potent cytotoxic molecules against human colorectal cancer cells, which exert resistance against anti-EGFR therapies." (PMID 29593231, 2018).